EPHA5 (EPH receptor A5)
Diseases named in the same sentence as EPHA5 in open-access papers (continued):
Sharing a sentence is not in itself a finding about the gene and the disease.
lung carcinoma (9 papers, 2015 to 2025). "A recent basic study suggested that the mutations in EPHA5 could promote the migration and invasion of lung cancer cells by inhibiting the cytotoxicity of NK cells against cancer cells." (PMID 36123678, 2022). "Expression of endogenous EphA5 on the surface of representative lung cancer cells (H460 and H226 cells) was confirmed by flow cytometry." (PMID 40662373, 2025). "The implication of EPHA5 in cervical carcinogenesis expands its relevance beyond lung cancer and supports its potential as a cross-tumor biomarker." (PMID 40806980, 2025). "This technique was used to generate anti-EphA5 antibodies that have shown specific targeting of EphA5 expressing lung cancer cells." (PMID 33634116, 2021). "The study revealed that high EphA5 expression in lung cancer indicated higher locoregional recurrence and lower cumulative overall patient survival." (PMID 31956298, 2020). "Together, these results establish EphA5 overexpression as a mechanism of cellular radioresistance, with potential implications for the therapeutic use of IR in lung cancer." (PMID 25623065, 2015). "We initially tested two shRNA constructs targeting EphA5 (EphA5-shRNA1 and EphA5 shRNA2) in the human lung cancer cell line H460." (PMID 25623065, 2015). "Here we show that the receptor tyrosine kinase EphA5 is specifically overexpressed in lung cancer and is involved in regulating cellular responses to genotoxic insult." (PMID 25623065, 2015). "The presence of EphA5 in these sets of samples was assessed according to scores of expression, and the data were independently quantified by two lung cancer pathologists (I. I. W. and M. I. N.)." (PMID 25623065, 2015). "EphA5 was found to be expressed in human lung cancers (∼70%), and the intensity of staining was substantially greater in SCC (median = 86.67) compared with ACC (median = 66.67) (Wilcoxon rank sum test, p = 0.0005)." (PMID 25623065, 2015). "In this study, we introduce the tyrosine kinase receptor EphA5 as a key regulator of radiation resistance in lung cancer through its novel and direct role in DDR." (PMID 25623065, 2015). "Our immunohistochemical analysis showed that EphA5 is widely expressed in human lung cancer, particularly in squamous cell carcinoma and that those patients expressing EphA5 as a molecular marker are at much higher risk of radiotherapy failure and death." (PMID 25623065, 2015). "Next, we analyzed EphA5 expression by immunohistochemical staining with a commercial antibody on a lung cancer TMA." (PMID 25623065, 2015). "Having confirmed expression of EphA5 in lung cancer cells and in a large cohort of patient-derived samples, we attempted to study the function of EphA5 in lung cancer." (PMID 25623065, 2015). "Significantly, we revealed that the survival of EPHA5-mutant (Mut) LUAD patients was more favorable than that of EPHA5-WT patients in an immunotherapy setting, providing new insight into the search for predictive biomarkers for the immunotherapy response in lung cancer." (PMID 33288738, 2020). "Significance: EphA5 may serve as a novel biomarker of radioresistance and a candidate target for therapeutic intervention in human lung cancer." (PMID 25623065, 2015). "In addition, we produced a new monoclonal antibody against EphA5 that sensitizes lung cancer cells to IR in vitro and improves the overall survival of mice bearing human lung cancer xenografts in combination with radiation therapy." (PMID 25623065, 2015). "Because 11C12 cross-reacts with rat EphA5, but not with mouse EphA5, these studies were performed in a rat xenograft model of human lung cancer (H460 cells)." (PMID 25623065, 2015). "In conclusion, the therapeutic applications of EphA5-targeted therapy, together with its functions in the cellular response to DNA damage, identify EphA5 as a critical new target for therapeutic intervention in lung cancer." (PMID 25623065, 2015).
lung carcinoma (continued). "We hypothesized that inhibition of EphA5 activity would sensitize lung cancer cells to radiotherapy and offer a novel therapeutic strategy." (PMID 25623065, 2015). "Thus, to initiate the characterization of EphA5 as a potential molecular marker of lung cancer, we determined levels of EphA5 expression in several human lung cancer cell lines." (PMID 25623065, 2015). "Finally, we demonstrate that a new monoclonal antibody against human EphA5 sensitized lung cancer cells and human lung cancer xenografts to radiotherapy and significantly prolonged survival, thus suggesting the likelihood of translational applications." (PMID 25623065, 2015). "Indeed, our new monoclonal antibody against EphA5 (11C12), when administered in combination with radiotherapy, sensitized lung cancer cells to IR in vitro and improved the overall survival of mice bearing human lung cancer xenografts." (PMID 25623065, 2015). "Here, we identify EphA5 as a molecular target of lung cancer and as a novel regulator of IR-induced cell cycle checkpoint and DNA damage repair, with unexpected roles in the resistance of lung cancer to radiotherapy." (PMID 25623065, 2015). "One group of cell-binding peptides showed targeting specificity for human lung cancer cells; the corresponding surface receptor for some of these ligand peptides was suggested to be the RTK EphA5." (PMID 25623065, 2015). "In the absence of EphA5, lung cancer cells displayed a defective G1/S cell cycle checkpoint, were unable to resolve DNA damage, and became radiosensitive." (PMID 25623065, 2015).
glioma (6 papers, 2012 to 2025). A benign or malignant brain and spinal cord tumor that arises from glial cells (astrocytes, oligodendrocytes, ependymal cells). "We also observed transcripts that are more highly expressed in brain tissue than either other normal tissue (ISPD, C10orf107), or more highly expressed in normal brain tissue than glioma (EPHA5)." (PMID 28166733, 2017). "A recent report revealed that EphA5 expression was decreased in low-grade glioma tumor tissues and was further reduced in high-grade glioma tumor tissues compared to normal control brain tissues, which suggested a novel role of EphA5 as a tumor suppressor." (PMID 25609195, 2015). "Moreover, in bladder cancer, lower EphA5 levels paradoxically indicate better overall survival, whereas in glioma, elevated EphA5 expression correlates with tumor progression." (PMID 40806980, 2025). "Likewise, EphA5 was previously shown to be expressed in dormant tumors, downregulated once they switch to the angiogenic phenotype, and to gradually decrease with advanced tumor stage in tumor specimens of glioma patients." (PMID 22952847, 2012). "In addition, we investigated co-staining of dormancy markers EphA5, IGFBP5 and H2BK with selected neural and embryonic stem cell markers that we and others have previously shown to be relevant in gliomas." (PMID 29296224, 2017). "Initially, we determined the basal mRNA and protein expression of EphA5, IGFBP5 and H2BK in human non-stem glioma cell lines (A172, LN229 and U251MG) and several GBM primary cultures (basal expression of stem cell markers has been described by our group before)." (PMID 29296224, 2017).
lung adenocarcinoma (6 papers, 2014 to 2025). A carcinoma that arises from the lung and is characterized by the presence of malignant glandular epithelial cells. "In an immunotherapy cohort, mutations in EPHA5 in lung adenocarcinoma resulted in longer progression-free survival than the wild-type." (PMID 41415030, 2025). "Conversely, in lung adenocarcinoma, EPHA5 mutations correlate with enhanced immune infiltration and better immunotherapeutic responses." (PMID 40806980, 2025). "In lung adenocarcinoma, EPHA5 expression is positively correlated with EGFR mutation status and lymph node metastasis, implicating its potential role in tumor progression and molecular classification." (PMID 40806980, 2025). "By integrating genomic, transcriptomic and clinical data from cohorts in public databases, we identified EPHA5 as the most common mutated gene of Eph receptors in lung adenocarcinoma (LUAD)." (PMID 33288738, 2020). "A recent study, conducted on the MSKCC immunotherapy cohort of lung adenocarcinoma patients, showed that the patients with mutations in EPHA5 could benefit more from immunotherapy as compared to those with wild-type EPHA5." (PMID 36123678, 2022). "Squamous cell lung carcinoma patients showed a no significant increased incidence of moderate/high EphA4 compared to those with adenocarcinoma, while moderate/high EphA5 and A7 expression was more frequently observed in lung adenocarcinoma patients compared to those with squamous cell carcinoma." (PMID 24495444, 2014). "We detected selective expression of EphA5 on the membrane and in the cytoplasm of cancer cells of both estrogen receptor-positive and TNBC, lung squamous cell carcinomas, and lung adenocarcinomas, as well as colon, pancreatic, gastric, ovarian, and urothelial cancers." (PMID 40662373, 2025).
neuropathy (6 papers, 2015 to 2021). A disorder affecting the nervous system that manifests with pain, tingling, numbness, and/or muscle weakness. "A recent study performed next generation sequencing on patients who developed significant neuropathy after paclitaxel, and identified variations of three related receptors, EPHA5/6/8, that correlated with susceptibility to paclitaxel-induced neuropathy." (PMID 28912674, 2017). "Older age, hyperglycemia, and obesity or poor nutritional status, such as single-nucleotide polymorphisms (SNPs) in the FGD4, EPHA5, and FZD3 genes and ABCB1 and GSTP1 polymorphisms, have been associated with the development of taxane-related neuropathy." (PMID 33922821, 2021). "EPHA5, another protein in our scaffold network encoded by the upregulated gene and engaged in the nervous system development, was recently identified as associated with PTX-induced neuropathy in cancer patients." (PMID 33287223, 2020). "Risk factors for the development of chemotherapy-induced neuropathy include older age, prior exposure to neurotoxins, diabetes, folate/B12 deficiencies, inter-individual variations in CYP2C8*3, class IIa β-tubulin, FDG4, FZD3, EPHA5, and the WNT pathway, among others." (PMID 34944858, 2021). "On the other hand, CYP2C8, ABCB1, EPHA5, EPHA6 and TUBB2A were found to be associated with taxane-induced neuropathy in more than one study, but not to be associated with platinum-induced neuropathy." (PMID 26269716, 2015).
colorectal cancer (5 papers, 2015 to 2025). A primary or metastatic malignant neoplasm that affects the colon or rectum. "In esophageal adenocarcinoma, a gene signature that includes EPHA5 mutations predicted an improved response to neoadjuvant chemoradiotherapy in one study, whereas in colorectal cancer, reduced EphA5 expression is associated with lymph node metastasis, an advanced stage, and a poor prognosis." (PMID 40806980, 2025). "In the present work, we find that NOVA2 uniquely regulates a series of alternative splicing events of axon guidance related genes, including deleted in colorectal carcinoma (Dcc), Roundabout, Axon Guidance Receptor, Homolog 2 (Robo2), Slit homolog 2 (Slit2), and EPH Receptor A5 (Epha5)." (PMID 27223325, 2016).
gastric cancer (4 papers, 2020 to 2025). A primary or metastatic malignant neoplasm involving the stomach. "As a tumor suppressor gene, abnormal EPHA5 methylation was found in gastric cancer (GC) tissues and was linked to the initiation, progression and prognosis of GC." (PMID 36164608, 2022). "Previous researchers applied bisulfite next-generation sequencing and The Cancer Genome Atlas to seek biomarkers for GC, and DNA hypermethylation and reduced RNA expression levels of EPHA5 were detected in GC tissues compared with the corresponding non-gastric cancer tissues from the same case." (PMID 36164608, 2022). "EPHA1, EPHA2, EPHA3, EPHA5, EPHB2 and EPHB4 expression has been reported as 2-fold higher in stromal cells isolated from gastric cancer tissues compared with normal gastric tissue stromal cells." (PMID 34445116, 2021). "While this gene has not been directly linked to Hippo, the related EphA2 receptor was shown to regulate YAP in breast and gastric cancer cells and other EPHA receptors (EPHA4, EPHA5, EPHA7 and EPHA8) emerged as Hippo pathway activators in an siRNA screen in HEK293T cells." (PMID 40869130, 2025).
hepatocellular carcinoma (4 papers, 2015 to 2023). A malignant tumor that arises from hepatocytes. "In hepatocellular carcinoma, elevated EphA5 expression is associated with a higher grade of histological malignancy according to Edmondson and infiltration of blood vessels and bile ducts, suggesting that the receptor may affect cancer invasion and promote distant metastasis." (PMID 33007931, 2020). "Paradoxically, recent studies have demonstrated that the EphA5 gene was upregulated in high-grade hepatocellular carcinoma." (PMID 25609195, 2015). "And in high-grade hepatocellular carcinoma,the EphA5 gene was also demonstrated to be upregulated." (PMID 31956298, 2020).
ovarian serous carcinoma (4 papers, 2016 to 2025). "In ovarian serous carcinoma, positive EphA5 expression is associated with longer survival, and in esophageal squamous cell carcinoma, EphA5 knockdown promotes proliferation and invasion through the Wnt/β-catenin pathway." (PMID 40806980, 2025). "On the other hand, low EphA5 expression is associated with worse prognosis in ovarian serous carcinoma." (PMID 33007931, 2020). "However, in ovarian serous carcinoma, loss of EphA5 expression was found to be associated with high-grade and advanced FIGO stage." (PMID 31956298, 2020). "In current study, we found that loss of expression of EphA5 was more often found in high-grade and advanced FIGO stage in ovarian serous carcinoma." (PMID 27887627, 2016). "Our results show that EphA5 is a potential biomarker for distinguishing high-and low-grade ovarian serous carcinoma, and a potential prognostic marker in ovarian serous carcinomas." (PMID 27887627, 2016). "The expression of EphA5 protein was significantly decreased from normal fallopian tubes, benign ovarian serous tumors, ovarian serous borderline tumors to ovarian serous carcinomas (P < 0.001)." (PMID 27887627, 2016). "Identification of hypermethylated EphA5 DNA in ovarian serous carcinoma will improve our understanding of the mechanisms leading to the downregulation of EphA5 expression in ovarian tumorigenesis and can serve as valuable diagnostic marker." (PMID 27887627, 2016). "This study aims to investigate the expression of EphA5 protein in ovarian serous carcinoma, and its relationship to clinical pathological characteristics." (PMID 27887627, 2016). "EphA5 protein was differentially expressed in 61 samples of ovarian serous carcinoma." (PMID 27887627, 2016). "Here, we evaluated the expression of EphA5 protein in a set of normal fallopian tube, benign epithelial ovarian tumors, ovarian serous borderline tumors, and ovarian serous carcinomas samples to explore its roles in ovarian serous carcinoma." (PMID 27887627, 2016). "High and moderate expression of EphA5 was observed in 100% (20/20) of normal fallopian tube samples, 100% (24/24) of benign epithelial ovarian tumors, 76% (32/42) of ovarian serous borderline tumors, and 31% (19/61) of ovarian serous carcinomas." (PMID 27887627, 2016). "Our results show that EphA5 may be a potential biomarker for distinguishing high-and low-grade ovarian serous carcinoma and a potential prognostic marker." (PMID 27887627, 2016). "Immunostaining analysis demonstrated that the EphA5 protein was highly expressed in 100% (20/20) of normal fallopian tube samples, 100% (24/24) of benign epithelial ovarian tumors, 76% (32/42) of ovarian serous borderline tumors, and 31% (19/61) of ovarian serous carcinomas." (PMID 27887627, 2016). "The expression of EphA5 was decreased in ovarian serous carcinoma compared with normal fallopian tube." (PMID 27887627, 2016). "Our findings that EphA5 was absent in high-grade serous ovarian carcinoma indicate that EphA5 may be a new biomarker for distinguishing high- and low-grade ovarian serous carcinoma." (PMID 27887627, 2016).
melanoma (3 papers, 2021 to 2025). A malignant, usually aggressive tumor composed of atypical, neoplastic melanocytes. "IL-17A stimulation recruits ELAVL1 and PIAS2 via TRAF2, stabilizing EPHA5 mRNA and promoting melanoma cell proliferation and invasion." (PMID 40809015, 2025). "This concurs with findings that the TRAF2/PIAS2/ELAVL1/EPHA5 pathway is pivotal in IL-17A-induced melanoma." (PMID 40809015, 2025). "PAX3, a transcription factor involved in melanocyte development, the receptor tyrosine kinase KIT, CDKN1C, and EPHA5 were upregulated in the melanoma compared to the atypical nevus, while NTRK3 and ROS1 were downregulated in the same comparison." (PMID 35052351, 2021). "In addition, genes encoding protein tyrosine kinases, KIT and EPHA5, relevant receptors upstream of the MAPK pathway, are particularly highly expressed in the melanoma compared to BAP1-inactivated nevus." (PMID 35052351, 2021). "Induces EPHA5 via TRAF2 to recruit PIAS2 and ELAVL1 to promote melanoma development." (PMID 39906741, 2024). "IL-17 also induces EPHA5 via TRAF2 to recruit PIAS2 and ELAVL1 to promote melanoma development." (PMID 39906741, 2024).
ovarian carcinoma (3 papers, 2016 to 2025). A malignant neoplasm originating from the surface ovarian epithelium. "In ovarian cancer, specifically, disruptions in EPHA5 signaling are linked to enhanced tumor invasiveness, possibly aiding immune evasion and metastasis." (PMID 39925800, 2025). "A longer follow-up would have provided a more robust assessment of the patient’s response to therapy and potential late-emerging resistance mechanisms, offering deeper insights into the prognostic implications of BTK and EPHA5 mutations in ovarian cancer metastasis." (PMID 39925800, 2025). "Overall, the identification of BTK and EPHA5 mutations in this patient’s tumor highlights the expanding landscape of genetic drivers in ovarian cancer and underscores the potential for using precision medicine to address previously unidentified mutation- driven pathways." (PMID 39925800, 2025). "This is the first report on the panorama gene profile of ovarian cancer metastasis to axillary lymph node and we found two novel mutations (BTK pD326E and EPHA5 pD251E)." (PMID 39925800, 2025). "While axillary lymph node metastasis from ovarian cancer is rare, our case represents the first report of BTK pD326E and EPHA5 pD251E mutations contributing to such metastasis." (PMID 39925800, 2025). "In our next study, we will determine the relationship between expression level and the methylation status of EphA5 in ovarian cancer tissues." (PMID 27887627, 2016). "We discovered not only the common mutations including the tumor suppressive genes, metabolism-related genes, and DNA repair genes, but also the unique mutations in the BTK (D326E) and EPHA5 (D251E) genes adds further novelty, as these mutations have not been reported in ovarian cancer previously." (PMID 39925800, 2025).